SUV39H2 (SUV39H2 histone lysine methyltransferase)
Description:
Histone methyltransferase that specifically mediates trimethylation of 'Lys-9' of histone H3 (H3K9me3) using monomethylated H3 'Lys-9' (H3K9me1) as substrate. H3 'Lys-9' trimethylation represents a specific tag for epigenetic transcriptional repression by recruiting HP1 (CBX1, CBX3 and/or CBX5) proteins to methylated histones. Mainly functions in heterochromatin regions, thereby playing a central role in the establishment of constitutive heterochromatin at pericentric and telomere regions. H3 'Lys-9' trimethylation is also required to direct DNA methylation at pericentric repeats. SUV39H2 is targeted to histone H3 via its interaction with RB1 and is involved in many processes, such as cell cycle regulation, transcriptional repression and regulation of telomere length. May participate in regulation of higher-order chromatin organization during spermatogenesis (By similarity). Recruited by the large PER complex to the E-box elements of the circadian target genes such as PER2 itself or PER1, contributes to the conversion of local chromatin to a heterochromatin-like repressive state through H3 'Lys-9' trimethylation (By similarity).
Synonyms: KMT1B; FLJ23414
Tractability: Small molecule: a structure with a bound ligand is known; a high-quality ligand is known; it has a high-quality binding pocket. PROTAC: UniProt records ubiquitination sites on it; ubiquitination databases record sites on it; a small molecule that binds it is known.
Target class: Writer; Protein methyltransferase; Epigenetic regulator
Gene: Protein-coding gene on chromosome 10 (14,878,820 to 14,904,315, forward strand). Ensembl gene ENSG00000152455.
Subcellular location: Nucleus; Chromosome; Chromosome, centromere
Subcellular location (Human Protein Atlas): Mitochondria
Pathways (Reactome):
Chromatin organization: PKMTs methylate histone lysines
Gene Ontology:
Molecular function: histone H3K14ub reader activity; histone H3K9 trimethyltransferase activity; histone H3K9me2 methyltransferase activity; histone H3K9me2/3 reader activity; protein binding; S-adenosyl-L-methionine binding; zinc ion binding; histone H3 methyltransferase activity; histone H3K9 methyltransferase activity; transcription cis-regulatory region binding; histone methyltransferase activity
Biological process: cellular response to hypoxia; chromatin organization; chromatin remodeling; epigenetic programming in the zygotic pronuclei; heterochromatin formation; negative regulation of transcription by RNA polymerase II; pericentric heterochromatin formation; circadian rhythm; negative regulation of DNA-templated transcription; negative regulation of gene expression, epigenetic
Cellular component: chromatin; nucleus; pericentric heterochromatin; nucleoplasm; chromosome; chromosome, centromeric region; nuclear lumen
Genetic constraint (gnomAD): Loss-of-function variants: 9 observed, 42.79 expected, observed/expected ratio (o/e) 0.21, 90% interval 0.13 to 0.37. The upper end of that interval is the gene's LOEUF score, 0.37, which puts it in group 1 of 6, group 1 being the genes least tolerant of losing a copy. Missense variants: 256 observed, 482.89 expected, observed/expected ratio (o/e) 0.53, 90% interval 0.48 to 0.59. Synonymous variants: 157 observed, 164.75 expected, observed/expected ratio (o/e) 0.95, 90% interval 0.84 to 1.09.
Homologues: Orthologues: chimpanzee SUV39H2 (99% identical), macaque SUV39H2 (99% identical), dog SUV39H2 (98% identical), pig SUV39H2 (97% identical), rabbit SUV39H2 (97% identical), guinea pig SUV39H2 (93% identical), rat Suv39h2 (90% identical), mouse Suv39h2 (89% identical), tropical clawed frog suv39h2 (70% identical), Drosophila melanogaster G9a (27% identical), Caenorhabditis elegans met-1 (21% identical), Caenorhabditis elegans set-11 (19% identical), and 10 more. Paralogues in human: SUV39H1 (59% identical), EHMT1 (31% identical), EHMT2 (31% identical), SETDB1 (25% identical), ASH1L (23% identical), KMT2D (23% identical), NSD1 (23% identical), NSD3 (22% identical), SETDB2 (21% identical), KMT2C (21% identical), NSD2 (20% identical), KMT2A (20% identical), and 7 more.
Diseases named in the same sentence as SUV39H2 in open-access papers:
SUV39H2 is named in the same sentence as 44 diseases in open-access papers, as found by Europe PMC text mining. Sharing a sentence is not in itself a finding about the gene and the disease. The quoted sentences say what the papers report.
breast carcinoma (9 papers, 2016 to 2025). "Clinically, SUV39H2 is highly expressed in basal-like breast cancer and correlates with adverse prognosis in patients." (PMID 41551146, 2025). "Emerging evidence suggests that dysregulation of SUV39H2 contributes to aberrant histone methylation signatures, driving breast cancer progression." (PMID 41551146, 2025). "In murine MMTV-PyMT models of breast cancer, SUV39H2 and other histone methyltransferases are upregulated at metastatic lung sites compared to primary tumors and disseminated cells." (PMID 41551146, 2025). "SUV39H2 is overexpressed in leukemia, lymphoma, breast cancer, colorectal cancer, gastric cancer, and lung cancer." (PMID 33658396, 2021). "We showed that SUV39H2 was abundantly overexpressed in breast cancer cell lines using quantitative real-time PCR and western blot analysis, and siRNA-mediated SUV39H2 knockdown significantly decreased cancer cell viability in vitro." (PMID 30159125, 2018). "Knockdown of SUV39H2 in these two cell lines significantly decreased cell viability, compared to those treated with siNC, suggesting that SUV39H2 plays a critical role in breast cancer cell growth." (PMID 30159125, 2018). "As SUV39H2 is implicated in hormone-responsive regulation and metastatic potential, it may serve as a prognostic indicator and therapeutic target in TNBC and advanced-stage breast cancer." (PMID 41551146, 2025). "In the present study, we reported the development of novel SUV39H2 methyltransferase inhibitors, OTS193320 and OTS186935, with a common imidazo[1,2-a]pyridine scaffold, and characterized the biological importance of SUV39H2 inhibition in breast cancer cells." (PMID 30159125, 2018). "We next measured the levels of signature genes whose protein products could be pharmacologically targeted in breast cancer lines (AURKB, SUV39H1, SUV39H2 and KDM4B)." (PMID 27863398, 2016).
lung carcinoma (9 papers, 2014 to 2025). "Furthermore, we employed the TCGA data for survival analysis to reveal the potential prognostic value underlying the SUV39H2 overexpression in lung cancer tissue." (PMID 30348215, 2018). "SUV39H2 is overexpressed in many cancer tissues, such as leukemia, lymphomas, lung cancer, breast cancer, colorectal cancer, gastric cancer and hepatocellular cancer." (PMID 34357075, 2021). "SUV39H2 is overexpressed in many cancers, including lung cancer, acute lymphoblastic leukemia, osteosarcoma and glioma, and SUV39H2 knockdown resulted in the inhibition of glioma cell growth." (PMID 34357075, 2021). "Previous work in our laboratory demonstrated that SUV39H2-mediated H2AX methylation increases the formation of γ-H2AX in lung cancer cells and that inhibition of SUV39H2 enhances chemosensitivity of lung cancer cells to cisplatin or DOX." (PMID 30159125, 2018). "Both SUV39H1 and SUV39H2 were reported to catalyze the formation of H3K9me2 and H3K9me3, and also participated the cell cycle regulation in a variety of cells, including the epidermal stem and progenitor cells and lung cancer cells." (PMID 37306883, 2023). "Hence, the expression spectrum analysis of SUV39H2 in lung cancer cell lines was performed, and SUV39H2 overexpression was seen in cells of A549, LTEP, and GLC-82, all of which are lung adenocarcinoma cell lines." (PMID 30348215, 2018). "We subsequently conducted immunohistochemical analysis of SUV39H2 in lung cancer and normal tissues, and found that SUV39H2 was overexpressed in 217 out of 328 archival NSCLC cases in accordance with the Oncomine database, while no staining was observed in normal organs, except for the testis." (PMID 25487737, 2014). "SUV39H2 histone lysine methyltransferase (SUV39H2), a novel cancer-testis antigen, is immunogenic and elicits cytotoxic CD8+ T-cell (CTL) responses against colon and lung cancer cells." (PMID 35574342, 2022). "Among them, a compound, OTS193320, exhibited a high inhibitory effect against SUV39H2 enzymatic activity (IC50 of 22.2 nM) and a growth suppressive effect of SUV39H2-positive A549 lung cancer cells (IC50 of 0.38 μM)." (PMID 30159125, 2018).
colorectal cancer (8 papers, 2018 to 2025). A primary or metastatic malignant neoplasm that affects the colon or rectum. "SUV39H2 is involved in histone methylation (H3-K9 specific) and chromatin assembly and is linked to colorectal cancer proliferation and metastasis, but its function in NB has yet to be clarified." (PMID 39175876, 2024). "Another study showed that SUV39H2 promotes colorectal cancer proliferation and metastasis via tri-methylation of the SLIT1 promoter and suppression of SLIT1 transcription." (PMID 34357075, 2021). "Suv39h1 activity controls cell migration in breast and colorectal carcinoma cells, while the depletion of suv39h2 induces apoptosis and cell death in ALL cells." (PMID 30213075, 2018). "Overexpression of SUV39H2 is a common phenomenon in multiple cancer types, including hematopathies (e.g., leukemias and lymphomas), breast cancer, digestive system cancers (e.g., colorectal carcinoma), lung cancer, urinary and reproductive system cancers (e.g., prostate cancer), and Bowen’s disease." (PMID 39519018, 2024). "SUV39H2 directly binded to the SLIT1 promoter, suppressing SLIT1 transcription to enhance proliferation and metastasis in colorectal cancer." (PMID 37306883, 2023). "Analogously, SUV39H2 was reported to be recruited on the promoter of SLIT1 and promote the proliferation and metastasis of colorectal cancer, suggesting that the epigenetic modulation of SUV39H2 was of importance." (PMID 30348215, 2018).
non-small cell lung carcinoma (5 papers, 2014 to 2025). A group of at least three distinct histological types of lung cancer, including non-small cell squamous cell carcinoma, adenocarcinoma, and large cell carcinoma. "Another study identified SUV39H2 as a tumor suppressor and showed that SUV39H2 overexpression in a non-small cell lung cancer (NSCLC) cell line leads to the inhibition of cell growth and proliferation by inducing G1 cell cycle arrest." (PMID 34357075, 2021). "We previously reported that overexpression of SUV39H2 in various cancer types such as non-small cell lung cancer, bladder cancer and prostate cancer." (PMID 26183527, 2015). "Since the expression of SUV39H2 is restricted in testis in adult tissues and is significantly elevated in various cancer types such as non-small cell lung cancer, bladder cancer and prostate cancer, SUV39H2 appears to be an ideal target for development of anti-cancer treatment." (PMID 26183527, 2015). "Additionally, miR-142 targets ASH1L/KMT2H in leukemia and thyroid cancer, miR-675 regulates SUV39H2/KMT1B in liver cancer, miR-122 influences SUV39H1/KMT1A in hepatocellular carcinoma, and miR-101 modulates KMT6/EZH2 in non-small cell lung cancer (NSCLC), prostate, and renal cancers." (PMID 40761244, 2025).
glioma (4 papers, 2019 to 2025). A benign or malignant brain and spinal cord tumor that arises from glial cells (astrocytes, oligodendrocytes, ependymal cells). "Taken together, these data highlight that SUV39H2 is a potential biomarker for glioma and indicates the causal relationship between SUV39H2 and glioma tumorigenesis." (PMID 31636512, 2019). "Together, SUV39H2 can be a new biomarker and a new strategy for clinical glioma therapeutic regimens." (PMID 31636512, 2019). "We conducted a sphere formation experiment and discovered that SUV39H2 knockdown decreased the number of glioma tumorspheres." (PMID 31636512, 2019). "Here, we primarily elucidated that SUV39H2 is upregulated in human glioma tissues and glioma cell lines." (PMID 31636512, 2019). "Together, these results demonstrate that SUV39H2 promotes the proliferation of glioma cells by affecting cell cycle progression." (PMID 31636512, 2019). "Together, these data demonstrate that the knockdown of SUV39H2 promotes the chemosensitivity of glioma cells to TMZ treatment." (PMID 31636512, 2019). "In addition, SUV39H2 could be a diagnostic biomarker of glioma." (PMID 31636512, 2019). "Next, we demonstrated that SUV39H2 regulated cell growth and chemosensitivity in glioma by regulating hedgehog signaling." (PMID 31636512, 2019). "RT-qPCR analysis revealed that SUV39H2 mRNA was remarkably upregulated in 26 glioma tissues compared to their normal counterparts." (PMID 31636512, 2019). "To further confirm that HHIP was regulated by SUV39H2 in glioma, we examined the expression of SUV39H2 and HHIP in xenograft tumors using immunohistochemistry (IHC) staining." (PMID 31636512, 2019). "SUV39H2 knockdown inhibited cell proliferation and stemness and promoted the chemosensitivity of glioma cells in vitro." (PMID 31636512, 2019). "The results showed that SUV39H2 deficiency increased the percentage of apoptotic glioma cells induced by TMZ, which indicates that SUV39H2 deficiency makes glioma cells more sensitive to TMZ treatment." (PMID 31636512, 2019). "SUV39H2 knockdown represses cell growth and promotes cell chemosensitivity in glioma cells by upregulating HHIP expression." (PMID 31636512, 2019). "Moreover, prior studies also noted that SUV39H2 was highly expressed in glioma tissues and the knockdown of SUV39H2 induced the inhibition of proliferation, stemness and cell growth in glioma cell." (PMID 37306883, 2023). "In addition, SUV39H2 downregulates the hedgehog interacting protein in glioma cells, thereby promoting hedgehog signaling." (PMID 34357075, 2021). "Our findings delineate the role of SUV39H2 in glioma cell growth and chemosensitivity as a pivotal regulator of the hedgehog signaling pathway and may support SUV39H2 as a potential target for diagnosis and therapy in glioma management." (PMID 31636512, 2019). "SUV39H2 knockdown inhibits the growth of glioma cells in vitro and in vivo." (PMID 31636512, 2019). "Here, we report that SUV39H2 is highly expressed in human glioma tissues." (PMID 31636512, 2019). "Therefore, our results emphasize that the inhibition of SUV39H2 expression can be a target for glioma therapy." (PMID 31636512, 2019). "In summary, we found that SUV39H2 is highly expressed in glioma cells and glioma tissues." (PMID 31636512, 2019). "We found that SUV39H2 is necessary for the proliferation of glioma cells in vitro." (PMID 31636512, 2019). "We also observed that the RNA and protein levels of SUV39H2 in glioma cell lines were higher." (PMID 31636512, 2019). "Additionally, SUV39H2 is essential in regulating the growth of glioma cells in vitro and in vivo." (PMID 31636512, 2019). "Furthermore, to determine whether SUV39H2 regulates glioma progression in an HHIP-dependent way, we transfected shSUV39H2 or the combination of shSUV39H2 and shHHIP into U251 cells." (PMID 31636512, 2019). "In addition, SUV39H2 knockdown also significantly inhibited glioma cell growth in vivo." (PMID 31636512, 2019).
glioma (continued). "In summary, these data demonstrate that SUV39H2 regulates tumor growth and TMZ sensitivity in an HHIP-dependent manner in glioma cells." (PMID 31636512, 2019). "In our study, we found that SUV39H2 regulated the activity of the GLI1 reporter, and there was a reverse correlation between SUV39H2 and HHIP expression in glioma." (PMID 31636512, 2019). "In addition, SUV39H2 knockdown enhances stem cell properties and TMZ sensitivity in glioma cells by regulating the Hh pathway." (PMID 31636512, 2019). "SUV39H2 is highly expressed in many types of human tumors, while the function of SUV39H2 in the development and progression of glioma has never been elucidated." (PMID 31636512, 2019). "In the GSE4290 database, we also found that SUV39H1 has a reverse correlation with HHIP, which indicates that SUV39H2 and SUV39H1 may have mutual compensatory effects on tumor growth and chemosensitivity in glioma." (PMID 31636512, 2019). "However, SUV39H2, a homologous enzyme of SUV39H1, is upregulated in many cancers, but it is still unknown whether it is upregulated in glioma." (PMID 31636512, 2019).
lung adenocarcinoma (4 papers, 2018 to 2023). A carcinoma that arises from the lung and is characterized by the presence of malignant glandular epithelial cells. "In this study, we discovered that SUV39H2 is a potential oncogene in lung adenocarcinoma, whose expression was elevated in tumor tissues." (PMID 30348215, 2018). "In this research, we analyzed the chip assay of lung adenocarcinoma samples and identified SUV39H2 as a potential oncogene due to its overexpression in the tumor tissues." (PMID 30348215, 2018). "SUV39H2 is a potential oncogene in lung adenocarcinoma and osteosarcoma." (PMID 37974198, 2023). "SUV39H2 might be a potential oncogene in lung adenocarcinoma, mediating tumorigenesis and metastasis." (PMID 30348215, 2018). "Furthermore, we also uncovered the overexpression of some classical oncogenes (FOXA1, PCNA, EZH2) that were reported to mediate carcinogenesis in lung adenocarcinoma along with SUV39H2." (PMID 30348215, 2018). "Thus, we evaluated cancer genomic data in lung adenocarcinoma and functional small-interfering RNA (siRNA), to explore the clues of SUV39H2 overexpression and its pathological activity in tumor cell lines." (PMID 30348215, 2018). "SUV39H2 could potentiate the tumorigenesis and invasion of lung adenocarcinoma cells, probably by repressing OPTN and STOM." (PMID 30348215, 2018). "Compared to SUV39H1, the amplification percentage of SUV39H2 was much higher throughout the various stages of lung adenocarcinoma; guided by which, we found that the CNA and the expression of SUV39H2 shared a positive relation, leading to an explanation of its overexpression." (PMID 30348215, 2018).
prostate carcinoma (4 papers, 2014 to 2024). A carcinoma that arises from epithelial cells of the prostate gland. "Specifically, the knockdown of SUV39H2 in prostate cancer cells led to a marked reduction in the expression of key stemness markers, including SOX2, NANOG, CD44, CD133, and octamer-binding transcription factor 4 (OCT4)." (PMID 39703687, 2024). "The suppressor of variegation 3–9 homolog 2 (SUV39H2) was identified as a critical enhancer of CSC populations in prostate cancer." (PMID 39703687, 2024). "Expression profile analysis by complementary DNA microarray using a large number of clinical cases also revealed overexpression of SUV39H2 in cervical, bladder, oesophageal and prostate cancers, as well as in osteosarcomas and soft tissue sarcomas." (PMID 25487737, 2014). "Additionally, SUV39H2 knockdown significantly impaired cell viability in response to docetaxel treatment compared to control cells, indicating that SUV39H2 contributes to docetaxel resistance in prostate cancer." (PMID 39703687, 2024).
gastric cancer (3 papers, 2010 to 2025). A primary or metastatic malignant neoplasm involving the stomach. "In the present study, we first observed, to our knowledge, that the possible H3K9me3 binding protein CBX7 itself could initiate the specific formation of H3K9me3 via HMTase SUV39H2-dependent pathways in the p16 locus within gastric cancer cell lines." (PMID 21060834, 2010).